LINC01811 (long independently transcribed non-coding RNA 1811)
Gene: Long non-coding RNA gene on chromosome 3 (33,956,972 to 34,677,247, forward strand). Ensembl gene ENSG00000226320.
Diseases named in the same sentence as LINC01811 in open-access papers:
LINC01811 is named in the same sentence as 2 diseases in open-access papers, as found by Europe PMC text mining. Sharing a sentence is not in itself a finding about the gene and the disease.
LINC01811 shares sentences with these, for which no sentence is quoted: cancer (1 paper); colorectal cancer (1).